ING2 (inhibitor of growth family member 2)
Diseases named in the same sentence as ING2 in open-access papers (continued):
Sharing a sentence is not in itself a finding about the gene and the disease.
cancer (18 papers, 2006 to 2024). A tumor composed of atypical neoplastic, often pleomorphic cells that invade other tissues. "ING2 is known to activate p21 expression by modifying the methylation patterns at the p21 promotor; however, the loss of ING2 in cancer results in decreased expression of p21 and increased progression from G1 to S phase." (PMID 31575057, 2019). "Suberoylanilide hydroxamic acid (SAHA), an HDAC inhibitor used clinically for the treatment of cancer causes the dissociation of ING2 from the Sin3 deacetylase complex leading to de-repression of downstream genes and growth inhibition." (PMID 21124965, 2010). "This analysis revealed that 221 out of 9,892 (2.23%) human cancer samples included in the TCGA Pancancer study presented an alteration of ING2 gene and 161 of these 221 (73%) alterations were deletions." (PMID 31640185, 2019). "For example, Inhibitor of Growth 2 (ING2) is a tumor suppressor that is downregulated in human cancers." (PMID 31575057, 2019). "In immunohistochemical analysis, Zhao and colleagues analyzed expression profiles of the ING2 protein in normal versus cancer tissues." (PMID 31390718, 2019). "To explore further ING2 status in cancer, we used The Cancer Genome Atlas database to analyze alterations of the ING2 gene and the members of the mSin3A/HDAC complex." (PMID 31640185, 2019). "The rationale for doing so is that ING2 activation leads to up-regulation of p21 and Bax in a number of cancer cell lines." (PMID 25672483, 2016). "In contrast, it has been shown that ING1 and ING2 play an oncogenic role in some cancers, this situation being similar to TGF-β." (PMID 21052543, 2011). "Same to ING1, ING2 affects cancer development via epigenetic mechanisms." (PMID 36056353, 2022). "Accordingly, lack of ING2 expression has been reported with loss of function in a variety of cancers such as lung cancer and head and neck squamous cell carcinoma." (PMID 36056353, 2022). "Currently, ING2 has emerged as one potential intervening target for cancers." (PMID 34434929, 2021). "For all cancers in which they are negatively regulated, ING1 and ING2 protein levels decreased in the nucleus, suggesting a mutation closer to their NLS domain and/or an impaired interaction with a protein required to target ING1 and ING2 to the nucleus." (PMID 31878273, 2019). "Negative control of the cell cycle after overexpression of ING1 or ING2 in U2OS or normal skin fibroblast cells is consistent with the observations of overexpression of ING3 in cancer cells given their opposite involvements in HDAC and HAT complexes, respectively." (PMID 31905726, 2019). "However, ING2 expression profiles in cancers might be cancer- type-specific, as it is highly expressed in Burkitt’s lymphoma, cervical cancer, and colorectal cancer, suggesting a role as a candidate oncogene." (PMID 31752342, 2019). "Therefore, ING2 may play different roles in normal cells and cancers by mediating the TGF-β signaling pathway." (PMID 21052543, 2011). "Such a mechanism underscores the complex interplay between hormonal signaling and epigenetic modifiers in cancer progression, where ING1 and ING2 emerge as critical mediators of AR’s transcriptional repressive functions on key oncogenic drivers." (PMID 38813086, 2024). "The cumulative effect analyses by considering multiple CpG sites in each gene also demonstrated an obvious difference of methylation levels between normal and cancer samples (CASZ1: P 0.001, CDH13: P 0.001, ING2: P 0.001)." (PMID 30355852, 2018). "Thus, the function of ING2 may be different depending on the cancer type." (PMID 21052543, 2011).
cancer (continued). "The smallest region of overlap (region 4q35.1-4q35.2) encompasses the cancer associated genes TLR3, CDKN2AIP, ING2, CASP3 and SORBS2, none of which are thought to cause aberrant DNA methylation." (PMID 20444249, 2010).
kidney (1 paper, 2021). "The findings that ING2 mainly located at tubulointerstitial area and its expressions were altered under different kidney pathologies raised our interest to observe whether ING2 might have some impacts on TEC mitochondria." (PMID 34434929, 2021). "After the role of ING2, along with its modulating mechanism on MRPL12 and mitochondrial OXPHOS, in ischemic induced TEC injury was established, we continued to determine whether ING2 could serve as one intervening target for ischemic kidney injuries." (PMID 34434929, 2021).
kidney disease (1 paper, 2021). "IHC results that ING2 expression was altered in kidney tissue from AKI patients suggested that ING2 might be a pathogenic factor of this kind of kidney disease." (PMID 34434929, 2021). "As mitochondrial injury has been proposed as one common pathogenic event underlying ample kidney disorders, the identification of ING2 as one modulator of TEC mitochondrial homeostasis might be of significance in exploring potential intervening targets for these diseases." (PMID 34434929, 2021).
ING2 also shares sentences with these, for which no sentence is quoted: head and neck squamous cell carcinoma (2 papers); non-small cell lung carcinoma (2); acute lymphoblastic leukemia (1); adenocarcinoma (1); Azoospermia (1); endometrial cancer (1); fibrosarcoma (1); histiocytic sarcoma (1); oligospermia (1); pancreatic adenocarcinoma (1); pancreatic cancer (1).